HDAC6 (histone deacetylase 6)
Diseases named in the same sentence as HDAC6 in open-access papers (continued):
Sharing a sentence is not in itself a finding about the gene and the disease.
tumor (continued). "HDAC6 inhibition increased acetylation levels of α-tubulin without affecting histone acetylation, but it did not decrease tumor cell growth or block tumor cell migration or invasion." (PMID 37106761, 2023). "HDAC6 inhibition is a novel strategy to reverse CIPN without negatively interfering with tumor growth, but the mechanisms responsible for persistent reversal are not well understood." (PMID 36096670, 2022). "For instance, histone deacetylase 6 (HDAC6) inhibitors containing a naphthalimide skeleton, which is intrinsically fluorescent, were synthesized as inhibitor-based affinity probes (3 and 4) to detect the expression of HDAC6 in tumor cells." (PMID 36387103, 2022). "Among them, the expression of HDAC6 and KAT2B decreased in tumor tissue, while the rest increased." (PMID 36124029, 2022). "As consequence, the decrease of HDAC6 expression level significantly inhibits GB tumor growth in U87MG cells, both in vitro and in vivo, by increasing autophagic cancer cell death and eliciting the anti-tumor immune response." (PMID 35242765, 2022). "Taken together, our epigenetic drug screening identified HDAC6 inhibitors as potent sensitizers capable of promoting synthetic lethality of cysteine depletion in non-mesenchymal tumor cells." (PMID 34040090, 2021). "In breast cancer, HDAC6 promotes cell movement by acting on the nonhistone substrates, which enhance tumor cell movement, metastasis, and invasion." (PMID 34880761, 2021). "For example, HDAC6 plays a non-canonical role in the regulation of anti-tumor immune responses, as well as tumor invasion/dissemination in the setting of breast cancer." (PMID 34930302, 2021). "Notably, a combination treatment of a selective HDAC6 and doxorubicin (a DNA damage agent used as a standard therapy of EWS patients) dramatically inhibits tumor growth in two EWS murine xenograft models." (PMID 34345016, 2021). "Previous studies have investigated the regulation by specific HDACs on the PD-L1 expression of tumor cells, including HDAC6 and HDAC8, but the results are not very consistent." (PMID 34365463, 2021). "We demonstrated that there were no statistical differences in the levels of HDAC6 protein expression in the EWS cell lines as compared to other tumor cell lines." (PMID 34345016, 2021). "Regarding the expression of HDAC6, at first glance, we witnessed a band in all cell lines and, surprisingly, this band was more intense in the non-tumor cells, which was not consistent with the data obtained both by RT-qPCR and western blot of the tissues." (PMID 34073238, 2021). "Specific HDAC6 staining was found in both the nucleus and cytoplasm of EWS tumor cells." (PMID 34345016, 2021). "Altogether, our results suggest that low dose vorinostat, which is more selective for HDAC6 inhibition, could therefore represent an interesting therapeutic option for GBM especially in patients with EB1 overexpressing tumor with lower expected side effects." (PMID 33659042, 2021). "HDAC6 expression in MLNs but not primary tumor was an independent prognostic factor: patients with low expression of HDAC6 in MLNs had a better overall survival and disease-free survival." (PMID 34938729, 2021). "Currently there are two HDAC6-specific inhibitors in Phase I/II clinical trials, ACY-1215 and ACY-241, but much remains to be discovered concerning how HDAC6 interacts with DNA damage response (DDR) proteins and how HDAC6 inhibition impacts tumor DDR activity." (PMID 33020410, 2020). "The role of HDAC6 in tumour cell growth was further validated with CCK-8 assays; these results showed that HDAC6 overexpression promoted proliferation, whereas HDAC6 silencing significantly inhibited proliferation in these two kinds of cell lines." (PMID 32107418, 2020). "In tumor cells arising from oncolytic HSV-1 (oHSV) infection, histone deacetylase 6 (HDAC6) could promote the spread of oHSVs by modulating the trafficking of the oncolytic virus particles (OVs) through acetylation of the microtubule." (PMID 32457704, 2020).
tumor (continued). "Moreover, the fact that the SM1 tumor growth in HDAC6KO mice is reduced, suggests that the intervention of HDAC6 in the host is also an important component in the anti-tumor activity observed in the systemic use of HDAC6i." (PMID 30992475, 2019). "Although the selective silencing of HDAC6 in tumors reduces tumor growth in immunocompetent mice, this effect was not statistically significant." (PMID 30992475, 2019). "First, the mouse embryonic fibroblasts (MEFs) derived from wild-type or HDAC6-null embryos were transduced with retrovirus-expressing SV40 early region and RasG12V, which can transform cells from different sources into tumor cells, and then analyzed for anchorage-independent growth in soft agar." (PMID 30176876, 2018). "The present review expands our understanding of the current field and future directions and provides evidence that HDAC6, a cytosolic member of the HDAC family, may be an important target in anti-tumor strategies." (PMID 30176876, 2018). "Similarly, knockdown of HDAC4 enhanced radiation-induced cell death, that of HDAC6 reduced the migration and invasion activities of all HCC cell lines, and that of HDAC8 repressed tumor cell growth and induced apoptosis." (PMID 30140374, 2018). "Our in vitro studies showing enhanced ERK1/2 and AKT phosphorylation are corroborated by immunohistochemical data in tumor sections from GBM patients, also showing markedly stronger signals for HDAC6, EGFR, phosphorylated ERK1/2, and phosphorylated AKT compared to normal brain tissue." (PMID 30302275, 2018). "For instance, HDAC6 is overexpressed in advanced stages of HNSCC, suggesting that its activity may be important in determining tumor aggressiveness in oral cancers." (PMID 28704968, 2017). "The combination of SAHA and LY294002 yielded no enhanced inhibition of tumor growth, suggesting that HDAC6 and PI3K contribute to the same pathway, which leads to c-myc expression and tumor growth." (PMID 26848526, 2016). "However, a key role for intracellular HDAC6 and MT1-MMP transport in tumor cell metastasis has also been recently reported." (PMID 27622612, 2016). "HDAC6 did not change after Amblyomin-X treatment, but Bag3 increased; this occurred in both tumor cell lines." (PMID 25479096, 2014). "Since the activity of HDAC6 is not essential for tumour growth, HDAC6 inhibition likely does not contribute to single agent antitumoral activity of HDAC inhibitors." (PMID 18000499, 2007). "Panobinostat (LBH589) has been shown to disrupt the heat shock protein 90 (Hsp90)/HDAC6 complex and induce degradation of hypoxia-inducible factor 1α (HIF-1α), resulting in decreased vascular endothelial growth factor (VEGF) expression and subsequent inhibition of tumor angiogenesis and growth." (PMID 40450300, 2025). "Interestingly, histone deacetylase 6 (HDAC6) inhibition, suppressed transforming growth factor beta (TGF-β)/SRY-BOX2 (SOX2) and EMT pathway through tumor necrosis factor alpha (TNF-α) activation, and polarized macrophages from pro- to anti-tumor phenotypes." (PMID 40470218, 2025). "In this study, we demonstrated that ONECUT3 mediates HIF-1α deacetylation through histone deacetylase 6 (HDAC6), leading to the activation of HIF-1α transcription and its downstream glycolysis-related genes, thereby enhancing the Warburg effect and promoting tumor growth in CRC." (PMID 40032849, 2025). "Furthermore, it has been shown that, unlike the other HDACs, selective inhibition of HDAC6 impaired tumor growth and progression without inducing major adverse events in experimental animals." (PMID 38258065, 2023). "In addition to Hh hyperactivation, the overexpression of Histone deacetylase 6 (HDAC6) in GBM tumor promotes cell proliferation and TMZ resistance, indicating that HDAC6 targeting could represent a possible therapeutic strategy to counteract GBM progression." (PMID 36982845, 2023).
tumor (continued). "Overall, HDAC6 overactivity may contribute significantly to the initial steps of tumorigenesis and tumor progression through its influence on histone and non-histone proteins." (PMID 38004560, 2023). "Furthermore, HDAC6 enhances ADAM17 activity, increases the release of sIL-6R and promotes the M2 polarization of macrophages in the TME, thus allowing immune escape and promoting tumor development." (PMID 36270986, 2022). "In vitro, FL stromal cells decrease tumor B cell apoptosis through a set of partially resolved mechanisms, including the production of hedgehog ligands (Hh), BAFF and TGF-β, over- expression of ABC-type multi-drug transporters, and activation of a c-MYC/HDAC6 loop in tumor cells." (PMID 34956214, 2021). "Unfortunately, the mechanism of HDAC6 in tumor metabolism and tumor immunity is not yet precise." (PMID 34485153, 2021). "In addition to histone regulation, HDAC6 also affects tumor cell motility by regulating non-histone substrates." (PMID 34485153, 2021). "Interestingly, that same more intense band in the NHA line did not correspond to the height of HDAC6 but was slightly below the bands observed in the tumor cells." (PMID 34073238, 2021). "In addition, sensitivity of EWS cell lines to HDAC6 inhibition is higher than other tumor or non-tumor cell lines." (PMID 34345016, 2021). "The absence of HDAC6 in tumor cells significantly reduced tumor growth." (PMID 30992475, 2019). "In accordance, immunoblotting analysis of mice tumor tissues indicated WT rMIIP but not rMIIP S303A underwent S303 phosphorylation during tumor growth, and RelA Ac-K310 levels was attenuated in tumor tissues from cells with rMIIP S303A expression in a HDAC6 dependent manner." (PMID 29038521, 2017). "However, we did not observe any significant difference in HDAC2 and HDAC6 levels in tumor samples and adjacent normal controls." (PMID 26000099, 2015). "Notably, elevated HDAC-1 expression was significantly associated with increased tumor proliferative capacity, enhanced HDAC-4 expression with the absence of distant metastases and elevated HDAC-6 expression with earlier histopathological stage." (PMID 26502922, 2015). "Furthermore, tumor aggressiveness and survival may besignificantly affected by the expression of just one gene (HDAC11 in GLand HDAC4 and HDAC6 in ODIII)." (PMID 25791281, 2015). "Since HDAC6 also plays an important role in mitophagy and HDAC inhibitors are able to directly target ATG proteins interfering with this pathway, it is reasonable to speculate that HDAC6 inhibition affects mitophagy, leading to a block of tumor proliferation and self-renewal." (PMID 34944907, 2021). "Therefore, the simultaneous targeting of c-Myc and HDAC6 using the bromodomain and extra terminal protein family members inhibitor JQ1 and the HDAC6 inhibitor ricolinostat (ACY-1215) can effectively induce apoptosis of MM tumor cells in xenograft mice and inhibit proliferation." (PMID 32676030, 2020). "However, a correlation of intracellular distribution of HDAC6 with tumor progression is lacking." (PMID 26388610, 2015). "Despite changes to immunoregulatory B-cell phenotype, HDAC6 silencing or inhibition did not induce tumor-free survival in CLL-bearing mice, but rather delayed tumor progression." (PMID 33329575, 2020). "We found consistent results with tumor growth after injecting scramble A375 cells for 3 weeks; the null mice (n = 10) group lost four mice, whereas the HDAC5 or HDAC6 knockdown groups had no mice dead." (PMID 26747087, 2016). "b The dot-plots show the HDAC6 scores in the inflammatory breast cancer (IBC) and non-IBC primary tumor series when these samples were stratified based on their HR status (left) and their PAM-50 molecular subtype (right)." (PMID 26643555, 2015). "While HDAC2, HDAC3 and HDAC6 showed increased protein levels, the RNA levels either did not change (HDAC2 and HDAC3) or even decreased (HDAC6) in tumor samples." (PMID 23951168, 2013).
tumor (continued). "Consistent with their investigation, we showed similar results in an HDAC6 knockdown NSCLC cell line, suggesting that this observation is not tumor type specific." (PMID 22957056, 2012). "However, the specific regulatory mechanism of HDAC6 on PD-L1 is not clear, and whether ACY-1215 can improve the therapeutic effect of anti-PD1/PD-L1 and its function in anti-tumor immunity need to be further clarified." (PMID 38231305, 2024). "Here we showed that the combination of 5-FU with the HDAC6 inhibitor Tubastatin A, designed to target both the more committed CRC cells (by 5-FU) and the small but chemoresistant CSC fraction (by Tubastatin A), dramatically inhibited tumor growth in vivo with no significant in vivo toxicity." (PMID 30804456, 2019). "However, since M89b has no anti-tumor activity in a PDAC–PDX without GAL2R expression, it appeared that either M89b failed to translocate across the cellular and nuclear membranes to reach HDAC6 in tumor cells or the inhibition of HDAC6 by M89b in vivo was incapable of yielding an anti-tumor effect." (PMID 37373336, 2023).
neurodegenerative disease (63 papers, 2010 to 2026). A disorder of the central nervous system characterized by gradual and progressive loss of neural tissue and neurologic function. "Mercaptoacetamides have emerged as promising selective inhibitors of HDAC6, a target implicated in neurodegenerative diseases and immune regulation." (PMID 40284012, 2025). "In recent years, many studies have revealed that HDAC6 is implicated in multiple neurodegenerative diseases including PD." (PMID 37373121, 2023). "The potential role of HDAC6 in regulating cellular redox homeostasis has been previously implicated in the pathogenesis of several neurodegenerative diseases." (PMID 32660051, 2020). "HDAC6 also shuttles between the nucleus and cytoplasm and it is associated with a variety of disorders from cancer to neurodegenerative disease." (PMID 27993690, 2017). "In various neurodegenerative diseases, the mechanisms underlying HDAC6 interaction with other proteins seem to be a promising approach in understanding the modulation of HDAC6 activity." (PMID 23356410, 2013). "Thus the interplay between RanBPM and HDAC6 that we have uncovered in this study may also help understand the cellular pathology underlying protein aggregation in neurodegenerative diseases." (PMID 24795145, 2014). "Thus, dysregulation of HDAC6 activity by loss of p62 could affect the stability of microtubules leading to neurodegenerative disease." (PMID 24086678, 2013). "The testing of an HDAC6 inhibitor in mouse models of neurodegenerative disease would require multiple weeks of dosing, and thus oral compound administration in drinking water or chow would be a preferred route of administration." (PMID 41330635, 2026). "HDAC6 is also a possible therapeutic target to be explored in the treatment of neurodegenerative diseases such as AD and other disorders related to the Tau protein." (PMID 40284012, 2025). "The selective inhibition of class IIb HDACs is of interest since it has potential for application in the treatment of neurodegenerative diseases, especially regarding HDAC6." (PMID 40284012, 2025). "The identification of potent and effective HDAC6 inhibitors is significant for the development of novel therapeutic approaches in neurodegenerative diseases." (PMID 39598445, 2024). "In agreement with this proposal, inhibition of HDAC6 restores both normal α-tubulin acetylating levels and axonal transport in these neurodegenerative diseases." (PMID 37106761, 2023). "To note, the inhibition of HDAC6 is considered a good strategy to contrast several neurodegenerative diseases, such as peripheral neuropathy, and, in particular, axon regeneration by increasing microtubule stability in the axonal shaft." (PMID 37569662, 2023). "Recent studies and reports have shown that selective HDAC6 inhibition is a good way to fight neurodegenerative diseases like Alzheimer, Huntington, and Parkinson." (PMID 37638049, 2023). "It is noteworthy that to date, the therapeutic potential in the treatment of neurodegenerative diseases has already been demonstrated for a number of HDAC6 inhibitors in a series of preclinical studies." (PMID 37298694, 2023). "In some cases, e.g., neurodegenerative diseases, the use of inhibitors of the deacetylase HDAC6 has shown some therapeutic effects, namely, rescue of the phenotype of those diseases." (PMID 37106761, 2023). "Although HDAC6 has been reported as a potential therapeutic target for autoimmune and neurodegenerative diseases, only one study has reported the therapeutic potential of HDAC6 inhibitors against MS17." (PMID 34262061, 2021). "Analysis of HDAC6 molecules has revealed multifunctional domains that affect multiple events known to be altered during neurodegenerative disease." (PMID 33374719, 2020). "Regarding interplay between autophagy and the UPS, HDAC6 was recently found to be a key molecule in many neurodegenerative diseases." (PMID 33282865, 2020).